MGMT (O-6-methylguanine-DNA methyltransferase)
Diseases named in the same sentence as MGMT in open-access papers (continued):
Sharing a sentence is not in itself a finding about the gene and the disease.
pleomorphic xanthoastrocytoma (2 papers, 2021 to 2025). A WHO grade ll astrocytic tumor with a relatively favorable prognosis. "The methylation-based classification suggested anaplastic pleomorphic xanthoastrocytoma (-like) (PXA, score 0.99, Classifier 12.5), no MGMT promotor methylation, and the derived CNV profile indicated a homozygous deletion (HD) of CDKN2A/B." (PMID 41331048, 2025).
pleural mesothelioma (2 papers, 2013 to 2021). A neoplasm that arises from the mesothelial cells of the pleura. "We collected the methylation profile of pleural mesothelioma, and found 8 novel interactors to be hypomethylated in pleural mesothelioma versus non-tumor pleural tissue, namely, ACVR1B, IL6, MGMT, NRG1, OAT, PHLDA2, PLAUR and TNC." (PMID 33916178, 2021).
Thrombocytopenia (2 papers, 2005 to 2024). A reduction in the number of circulating thrombocytes. "After five days of TMZ treatment, the median MGMT activity in PBMCs dropped; low MGMT activity was associated with a higher degree of thrombocytopenia." (PMID 38817857, 2024). "In summary, temozolomide treatment for 5 days depleted MGMT in peripheral mononuclear cells in at least 76% of patients and low MGMT activity was correlated with severe thrombocytopenia during the first treatment cycle." (PMID 16136028, 2005). "Median MGMT activity in PBMCs decreased after 5 days of temozolomide treatment: low MGMT activity correlated with increased severity of thrombocytopenia." (PMID 16136028, 2005).
transitional cell carcinoma of the bladder (2 papers, 2014 to 2018). "Our results suggest that epigenetic silencing of RASSF1A, APC and MGMT genes is strongly associated with invasive high grade urothelial bladder cancer." (PMID 24790823, 2014). "NIM was found to be higher for RASSF1A, APC and MGMT in muscle invasive high grade urothelial bladder cancer as compared to the non muscle invasive low grade cancer." (PMID 24790823, 2014). "When the mean normalized index of methylation of the genes was compared between non- muscle invasive low grade and muscle invasive high grade urothelial bladder cancer, the degree of hypermethylation was more prominent in the muscle invasive high grade group for RASSF1A, APC and MGMT (p < 0.001)." (PMID 24790823, 2014).
vulvar carcinoma (2 papers, 2017 to 2021). "MGMT methylation has been detected in 45% (13/20) and 36.7% (11/30) of vulvar carcinomas." (PMID 33426639, 2021).
xeroderma pigmentosum (2 papers, 2014 to 2024). Xeroderma pigmentosum (XP) is a rare genodermatosis characterized by extreme sensitivity to ultraviolet (UV)-induced changes in the skin and eyes, and multiple skin cancers. "Additionally, activation of nucleotide and base excision repair gene, including O-6-methylguanine-DNA methyltransferase and xeroderma pigmentosum complementation group C, was observed." (PMID 39159810, 2024).
AIDS (1 paper, 2009). A syndrome resulting from the acquired deficiency of cellular immunity caused by the human immunodeficiency virus (HIV). "Here we developed lentiviral anti-HIV vectors that also contain a P140K MGMT transgene cassette and evaluated these vectors in in vitro studies and also in a clinically relevant primate model for AIDS gene therapy." (PMID 19888329, 2009).
alcohol abuse (1 paper, 2025). The use of alcoholic beverages to excess, either on individual occasions ("binge drinking") or as a regular practice. "All significant differences in overall survival related to age, alcohol abuse, and educational level remained statistically significant after adjustment for MGMT promoter methylation status and EOR." (PMID 40576809, 2025).
alpha-thalassemia mental retardation syndrome (1 paper, 2021). "These may include MGMT promoter methylation, isocitrate dehydrogenase (IDH) mutations, telomerase reverse transcriptase (TERT) mutations, 1p/19q co-deletion and alpha-thalassemia mental retardation syndrome (ATRX) mutations." (PMID 34794398, 2021).
anaplastic ependymoma (1 paper, 2023). Anaplastic ependymoma is a rare, malignant type of ependymoma that most often arises in the supratentorial region of the brain of children and young adults and that manifests with variable symptoms including headaches, nausea, vision impairment, memory loss and difficulty walking. "Lack of MGMT promotor hypermethylation and high expression of MGMT were observed in 75% (total=12) of recurrent anaplastic ependymomas, which theoretically favored the trial of temozolomide in PSAE patients." (PMID 36824145, 2023).
astroblastoma (1 paper, 2025). "However, the extended moleculo-histological examination 3 weeks later confirmed the diagnosis of an astroblastoma with MN1-alteration and unmethylated MGMT promoter methylation status (MGMT-STP27)." (PMID 39953192, 2025).
autoimmune disease (1 paper, 2023). A disorder resulting from loss of function or tissue destruction of an organ or multiple organs, arising from humoral or cellular immune responses of the individual to their own tissue constituents. "However, further experiments are needed to explore the functional role of NF2, FAM3B, and MGMT in BD and other autoimmune diseases." (PMID 37264476, 2023).
Azoospermia (1 paper, 2023). Absence of any measurable level of sperm,whereby spermatozoa cannot be observed even after centrifugation of the semen pellet. "MGMT downregulation has also been shown in patients with azoospermia, solidifying its role as an integral gene for testicular function." (PMID 37508506, 2023).
biliary tract cancer (1 paper, 2022). "The impact of MGMT inactivation in patients with advanced biliary tract cancer (BTC) is not established." (PMID 35621918, 2022).
Cervical Dysplasia (1 paper, 2023). "Changes in MGMT levels were detected in early-stage cervical dysplasia (ASC-HS/LSIL)." (PMID 37834832, 2023).
chondrosarcoma (1 paper, 2019). A malignant cartilaginous matrix-producing mesenchymal neoplasm arising from the bone and soft tissue. "Furthermore, temozolomide sensitivity in chondrosarcoma cell lines appears to be associated with MGMT RNA expression and methylation of the CpG island located in the promoter." (PMID 31810230, 2019). "IDH mutations cause hypermethylation of DNA in tumors, including chondrosarcoma, and this epigenetic modification may reduce MGMT mRNA expression." (PMID 31810230, 2019). "It is conceivable that MGMT expression or promoter methylation could be viable biomarkers for temozolomide mono- or combination therapy in chondrosarcoma." (PMID 31810230, 2019). "Our study also establishes that a subset of chondrosarcomas may harbor a nonclassical DNA repair deficiency related to a low DNA damage sensing capacity, low MGMT expression, or a defect more downstream in the homologous recombination pathway." (PMID 31810230, 2019). "Therefore, we investigated the methylation status of the MGMT promoter and effects on RNA expression in our chondrosarcoma cell line panel with or without long-term treatment with AGI-5198 or D-2-HG." (PMID 31810230, 2019). "Overall, these data indicated that the effectivity of temozolomide as either single or combination therapy in chondrosarcoma is not determined by the IDH mutation status and may be associated with other molecular differences between cell lines, such as MGMT expression." (PMID 31810230, 2019).
chronic gastritis (1 paper, 2021). Inflammation of the stomach that is chronic in nature. "Chronic gastritis induced by Helicobacter pylori showed MGMT promoter hypermethylation based on accelerated NF-κB signaling." (PMID 33917711, 2021).
clear cell carcinoma (1 paper, 2007). "Similarly, MGMT, a second repair enzyme encoding gene, was methylated in a single cell line ES-2, established from a human primary clear cell carcinoma, but not in any clinical samples." (PMID 17623056, 2007).
colon adenoma (1 paper, 2025). An adenoma that arises from the colon. "The fact that MGMT methylation has been detected in colon adenomas as well as normal colon mucosa located 10 cm from the tumor borders, suggests the presence of normal tissue epimutations which, potentially, may act as cancer precursors." (PMID 39980037, 2025).
congenital heart defects (1 paper, 2021). "Furthermore, genetic variants of SHMT1, BHMT, MGST1, MGMT, MTHFS, GNMT, and TRDMT1 were associated with an increased risk of congenital heart defects after prenatal antidepressant exposure." (PMID 33981330, 2021).
demyelinating CNS diseases (1 paper, 2021). "Our study is, therefore, the first to analyze MGMT promoter methylation in a variety of non-neoplastic CNS diseases, and we report cases of variable MGMT hypermethylation in infectious, inflammatory and demyelinating CNS diseases, as well as in those resulting in damage to the myelin sheath." (PMID 33917711, 2021).
demyelinating disease (1 paper, 2021). A broad group of disorders that affect the myelin sheaths that cover the neurons. "While this gives new insights into epigenetic and pathophysiological processes involved in de- and remyelination, which might offer new therapeutic opportunities for demyelinating diseases in the future, it also reduces the specificity of MGMT hypermethylation as a tumor biomarker." (PMID 33917711, 2021). "Interestingly, no samples from the group of infectious non-demyelinating diseases had MGMT promoter methylation rates higher than those in healthy controls, which stands in contrast to the findings in extra-CNS samples." (PMID 33917711, 2021).
duodenal adenocarcinoma (1 paper, 2016). A carcinoma that arises from glandular epithelial cells of the duodenum. "O6-methylguanine-DNA methyltransferase (MGMT) methylation status has not been extensively investigated in duodenal adenocarcinoma (DA)." (PMID 27643594, 2016).
eye cancer (1 paper, 2025). "Also, another important enzyme that is associated with this eye cancer is MGMT (O6- methylguanine-DNA methyltransferase), a DNA repair enzyme." (PMID 41150792, 2025).
female infertility (1 paper, 2021). Diminished or absent ability of a female to achieve conception. "However, approximately 50% of TMZ-treated GBM patients do not respond to TMZ because their tumors overexpressed O6-Methylguanine-DNA Methyltransferase (MGMT), and most patients experience serious side effects including bone marrow suppression and female infertility." (PMID 34488821, 2021).
Fibroadenoma (1 paper, 2011). A benign tumor of the breast characterized by the presence of stromal and epithelial elements. "We have identified the methylation of five cancer-related CpG islands in the giant fibroadenoma tissue: ESR1, MGMT, WT-1, BRCA2 and CD44." (PMID 22011321, 2011).
fibrosis (1 paper, 2018). the formation of excess fibrous connective tissue in an organ or tissue in a reparative or reactive process. "The biological relevance of the other two genes, retinol-binding protein 5 (RBP5) and O6-methylguanine-DNA methyltransferase (MGMT), both of which were hypomethylated in these studies, to the development of NAFLD-related fibrosis remains unknown." (PMID 30005700, 2018).
gallbladder carcinoma (1 paper, 2020). "Both MGMT methylation and mismatch repair status were related to poor prognosis in gallbladder carcinoma and extrahepatic cholangiocarcinoma." (PMID 32724874, 2020).
gastric leiomyoma (1 paper, 2014). A rare benign smooth muscle neoplasm arising from the wall of the stomach. "The methylation of MLH1, MGMT, and APC has been described in GISTs, but to the best of our knowledge this is the first time that the methylation of these genes has been associated with gastric leiomyoma." (PMID 25544907, 2014). "The genes found methylated in the gastric leiomyoma play different functions in the cell: MLH1, MSH3, MGMT, and MSH6 participate in DNA repair functions whereas APC gene participates in cell proliferation." (PMID 25544907, 2014).
hepatitis C (1 paper, 2017). "Increased MGMT expression in patients ≥ 40 years' old may reflect lower MGMT methylation levels which have been linked with hepatitis C and non-alcohol associated HCC." (PMID 29254188, 2017).
hepatoblastoma (1 paper, 2022). Hepatoblastoma (HB) is a malignant hepatic tumor and is the most common pediatric liver cancer. "For example, METTL3-mediated m6A mRNA methylation promoted the proliferation of hepatoblastoma through the regulation of CTNNB1, while METTL3 promoted temozolomide resistance by increasing the expression of MGMT and ANPG." (PMID 35571106, 2022).
Hyperkeratosis (1 paper, 2007). Hyperkeratosis is a histopathological term defining a thickened stratum corneum and may be present in many different skin conditions, with many possible overlaps. "The positive rates for MGMT mRNA were 18, 42, 69, and 73% for the carcinoma, precarcinoma, hyperkeratosis, and common pathological changes groups, respectively." (PMID 17450239, 2007).
hypothyroidism (1 paper, 2025). Abnormally low levels of thyroid hormone. "Conversely, Isocitrate Dehydrogenase 1 (IDH1) mutation, hypothyroidism, and O6-Methylguanine-DNA Methyltransferase (MGMT) promoter methylation were identified as protective factors." (PMID 40873733, 2025).
insulinomas (1 paper, 2021). "Hypermethylation of promoters of RASSF1 and MGMT genes appears to be an epigenetic marker of MEN1 insulinomas or MEN1 NF-pNETs, respectively, suggesting that they could be promising selective therapeutic targets for these two types of pancreatic tumors." (PMID 33919851, 2021). "The hypermethylation of MGMT promoter has been described in about 40% of sporadic pNETs, 44.7% of MEN1 NF-pNETs, and only 8.3% of MEN1 insulinomas." (PMID 33919851, 2021).
leukopenia (1 paper, 2006). "Grade 3–4 leukopenia was observed in three patients with methylated MGMT promoter and in one patient with unmethylated MGMT promoter, lymphopoenia grade 3 was observed in four patients with methylated MGMT promoter, and in one with unmethylated MGMT promoter." (PMID 17024124, 2006).
mesothelioma (1 paper, 2025). A usually malignant and aggressive neoplasm of the mesothelium which is often associated with exposure to asbestos. "Similarly, in mesothelioma cells, high SLFN11 expression correlated with response to PARP inhibitors, and combination with temozolomide enhanced the sensitivity of cells with low MGMT expression, further supporting the broad potential of SLFN11 as a biomarker of DNA damage response." (PMID 40766331, 2025).
metabolic syndrome (1 paper, 2024). A cluster of metabolic risk factors for CARDIOVASCULAR DISEASES and TYPE 2 DIABETES MELLITUS. "Those without metabolic syndrome tended to have a higher prevalence of gross total resection, methylguanine methyltransferase (MGMT) methylation, and epidermal growth factor receptor (EGFR) amplification." (PMID 39518104, 2024).
mismatch repair deficiency (1 paper, 2023). "Signature 11, which is associated with exposure to temozolomide plus MGMT promoter and/or mismatch repair deficiency, was indeed present in tumors with previous exposure to the drug." (PMID 37492101, 2023).
non-Hodgkin lymphoma (1 paper, 2020). Distinct from Hodgkin lymphoma both morphologically and biologically, non-Hodgkin lymphoma (NHL) is characterized by the absence of Reed-Sternberg cells, can occur at any age, and usually presents as a localized or generalized lymphadenopathy associated with fever and weight loss. "Temozolomide with good CNS penetration and low toxicity is an oral alkylating agent that affects O6-methylguanine-DNA-methyltransferase (MGMT) status, which are also proved to be effective against non-Hodgkin’s lymphoma." (PMID 30712191, 2020).
oropharynx tumors (1 paper, 2020). "In the present study with HPV-negative oral and oropharynx tumors, only DAPK and MGMT showed consistent evidence of their potential as epigenetic markers, with considerable levels of hypermethylation in cancer cells and, for MGMT, prognostic relevance." (PMID 32870234, 2020).
pancreatic adenocarcinoma (1 paper, 2009). "RASSF 1A was methylated in two patients, while the MGMT gene was methylated only in the patient with poorly differentiated pancreatic adenocarcinoma." (PMID 22276000, 2009).
pharyngeal cancer (1 paper, 2009). "Our results suggest that MGMT hypermethylation is one of the prognostic factors in oral and pharyngeal cancer patients' survival; similar findings were reported for head and neck patients in general by some authors but not by others." (PMID 19807915, 2009). "In the study described herein, we tested the association between promoter methylation and survival in a cohort of 88 oral and pharyngeal cancer patients, focusing on three target genes: the DNA repair gene MGMT and the tumor suppressor genes CDKN2A and RASSF1." (PMID 19807915, 2009). "The association between degree of MGMT hypermethylation and oral and pharyngeal cancer survival has not been reported before to our knowledge." (PMID 19807915, 2009).
pharyngeal tumors (1 paper, 2009). "We evaluated 88 primary oral and pharyngeal tumors for methylation of the promoter for the DNA repair gene MGMT and the tumor suppressor genes CDKN2A and RASSF1 using methylation-specific PCR." (PMID 19807915, 2009). "The promoter methylation status of the DNA repair gene MGMT and the tumor suppressor genes CDKN2A and RASSF1 were evaluated by methylation-specific PCR in 88 primary oral and pharyngeal tumors and correlated with survival and tumor recurrence." (PMID 19807915, 2009).
premalignant oral lesions (1 paper, 2014). "Pertinently, in the present study, we observed MGMT promoter methylation in 39% and 57% blood samples of patients with premalignant oral lesions and OSCC, respectively." (PMID 24991542, 2014). "Known risk factors for OSCC, namely tobacco, bidi, alcohol, and pan masala consumption, were found to contribute to promoter region methylation of both MGMT and p16 genes in controls, premalignant oral lesions, and OSCC groups." (PMID 24991542, 2014). "High promoter methylation frequency of MGMT and p16 genes was observed in patients with premalignant oral lesions and OSCC who were tobacco chewers and bidi smokers indicating contribution of these risk factors to gene silencing by promoter hypermethylation." (PMID 24991542, 2014). "The MGMT gene methylation in the OSCC group was significantly higher than that observed for all subgroups of premalignant oral lesions (P = 0.0379 for tissue and 0.0468 for blood samples)." (PMID 24991542, 2014). "As compared to controls, MGMT promoter methylation was significantly higher in tissue and blood samples of premalignant oral lesions and OSCC." (PMID 24991542, 2014). "Significant downregulation of MGMT and p16 gene expression was observed in both tissue and blood samples from premalignant oral lesions and OSCC patients." (PMID 24991542, 2014).
rectal adenocarcinoma (1 paper, 2019). "In this study, MGMT expression and MGMT promoter methylation status were evaluated in rectal adenocarcinoma patients after chemoradiotherapy treatment in order to determine their status and relevance as prognostic biomarkers." (PMID 31199091, 2019).
sarcopenia (1 paper, 2025). Progressive decline in muscle mass due to aging which results in decreased functional capacity of muscles. "Moreover, our study advances this field by using established sex‐specific cutoffs to define sarcopenia, analyzing treatment‐homogeneous cohorts, and incorporating key molecular information (i.e., MGMT status)." (PMID 40260649, 2025).
spinal cord glioma (1 paper, 2020). A neoplasm that arises from glial cells in the spinal cord. "This may be due to the low rate of MGMT promoter methylation in spinal cord gliomas; this was also observed in our study." (PMID 32228694, 2020).
T-cell lymphomas (1 paper, 2011). "Beyond confirming our preliminary evidences, it would be of interest to study the impact of AGT expression and MGMT promoter methylation status on fotemustine activity in T-cell lymphomas." (PMID 21752099, 2011).